ZDHHC13 (zDHHC palmitoyltransferase 13)
Description:
Palmitoyltransferase that could catalyze the addition of palmitate onto various protein substrates (By similarity). Palmitoyltransferase for HTT and GAD2. May play a role in Mg(2+) transport.
Synonyms: HIP14L; HIP3RP; FLJ10852; FLJ10941
Tractability: Antibody: UniProt predicts a signal peptide or a membrane-spanning region. PROTAC: ubiquitination databases record sites on it; its protein half-life has been measured.
Gene: Protein-coding gene on chromosome 11 (19,117,099 to 19,177,712, forward strand). Ensembl gene ENSG00000177054.
Subcellular location: Golgi apparatus membrane; Cytoplasmic vesicle membrane
Subcellular location (Human Protein Atlas): Vesicles; Golgi apparatus
Gene Ontology:
Molecular function: magnesium ion transmembrane transporter activity; palmitoyltransferase activity; protein-cysteine S-palmitoyltransferase activity
Biological process: positive regulation of canonical NF-kappaB signal transduction; magnesium ion transmembrane transport
Cellular component: endoplasmic reticulum; membrane; cytoplasmic vesicle membrane; Golgi membrane; Golgi-associated vesicle membrane; Golgi apparatus
Genetic constraint (gnomAD): Loss-of-function variants: 82 observed, 75 expected, observed/expected ratio (o/e) 1.09, 90% interval 0.91 to 1.31. The upper end of that interval is the gene's LOEUF score, 1.31, which puts it in group 5 of 6, group 1 being the genes least tolerant of losing a copy. Missense variants: 685 observed, 692.9 expected, observed/expected ratio (o/e) 0.99, 90% interval 0.93 to 1.05. Synonymous variants: 256 observed, 236.1 expected, observed/expected ratio (o/e) 1.08, 90% interval 0.98 to 1.2.
Homologues: Orthologues: chimpanzee ZDHHC13 (99% identical), macaque ZDHHC13 (98% identical), dog ZDHHC13 (92% identical), rabbit ZDHHC13 (92% identical), mouse Zdhhc13 (91% identical), pig ZDHHC13 (91% identical), guinea pig ZDHHC13 (91% identical), rat Zdhhc13 (91% identical), tropical clawed frog zdhhc13 (55% identical), zebrafish zdhhc13 (50% identical), Drosophila melanogaster Hip14 (36% identical). Paralogues in human: ZDHHC17 (48% identical), ANKRD35 (17% identical).
Diseases named in the same sentence as ZDHHC13 in open-access papers:
ZDHHC13 is named in the same sentence as 38 diseases in open-access papers, as found by Europe PMC text mining. Sharing a sentence is not in itself a finding about the gene and the disease. The quoted sentences say what the papers report.
alopecia (7 papers, 2010 to 2025). Hair loss usually from the scalp. "Compared with other PAT family member-defective mouse models, Zdhhc13-deficient mice exhibit severe phenotypes, including alopecia, osteoporosis, and amyloidosis." (PMID 28526873, 2017). "The Zdhhc13 deficient mice show the most severe phenotype with amyloidosis, alopecia, and osteoporosis." (PMID 24637783, 2014). "We have previously shown that mice carrying a recessive Zdhhc13 nonsense mutation causing a Zdhcc13 deficiency develop alopecia, amyloidosis and osteoporosis." (PMID 24637783, 2014). "The identification of target proteins of ZDHHC13 would be an important first step for understanding the molecular mechanisms underlying human alopecia, osteoporosis and many neurodegenerative diseases caused by protein misfolding and amyloidosis." (PMID 20548961, 2010). "In summary, we report that deficiency of a single palmitoyl acyltransferase (Zdhhc13) can cause severe systemic phenotypes, including failure to thrive, cachexia, osteoporosis, alopecia, multi-organs/systems dysfunction secondary to systemic amyloidosis and early death." (PMID 20548961, 2010). "In order to determine the precise role of ZDHHC13 in the organism, researchers bred Zdhhc13-mutant mice, which exhibited the phenotype of osteoporosis, alopecia, shortened lifespan, and multiple organ amyloidosis." (PMID 40153585, 2025). "We previously reported that in mice, deficiency of Zdhhc13, a member of the PAT family, causes severe phenotypes including amyloidosis, alopecia, and osteoporosis." (PMID 28526873, 2017). "The Zdhhc13 mutant mice also showed significant skin pathology with hypotrichosis, alopecia and loose skin with wrinkling and folding." (PMID 20548961, 2010). "Remarkably, Zdhhc13-truncated mutant mice develop alopecia, osteoporosis, and systemic amyloidosis; and the osteoporotic phenotype can be explained by the finding that protein palmitoylation regulates osteoblast differentiation through bone morphogenesis protein (BMP)-induced Osterix expression." (PMID 23586671, 2013). "However, we did not observe any alteration in Zdhhc13 level suggesting that the development of cyclic alopecia in K14-sPLA2-IIA homozygous mice is independent of cornifelin deficiency mediated cyclic alopecia as shown in Zdhhc13 mutant mice." (PMID 28912581, 2017).
amyloidosis (5 papers, 2010 to 2023). A disorder characterized by the localized or diffuse accumulation of amyloid protein in various anatomic sites. "Two other putative candidate genes, namely SLC10A2 and ZDHHC13, have been reported to be associated with amyloidosis in humans and/or mice in previous studies." (PMID 38136948, 2023). "Therefore, we propose that a deficiency of Zdhhc13 PAT activity may have caused amyloidosis in our mice." (PMID 20548961, 2010).
Huntington disease (5 papers, 2014 to 2025). Huntington disease (HD) is a rare neurodegenerative disorder of the central nervous system characterized by unwanted choreatic movements, behavioral and psychiatric disturbances and dementia. "Although a recent study of the Zdhhc13 gene-trap mouse model reported a Huntington’s disease phenotype, we did not observe this phenotype in our Zdhcc13 deficient mouse model." (PMID 24637783, 2014).
melanoma (5 papers, 2019 to 2025). A malignant, usually aggressive tumor composed of atypical, neoplastic melanocytes. "The results revealed that ZDHHC13 effectively suppressed metastasis in cells with WT CTNND1, but not in those with the C618S mutation, suggesting that ZDHHC13 suppresses melanoma metastasis primarily through CTNND1 palmitoylation in vitro." (PMID 41321310, 2025). "We further show that ZDHHC13 reshapes the immune microenvironment by altering melanoma lipid metabolism, reducing M2-like tumor-associated macrophages and slowing tumor growth in immunocompetent mice." (PMID 41321310, 2025). "Importantly, ZDHHC13 also reshapes the tumor immune microenvironment by suppressing lysophosphatidylcholine (LPC) synthesis in melanoma cells, leading to inhibition of M2-like tumor-associated macrophages that we show degrade E-cadherin via MMP12 expression." (PMID 41321310, 2025). "In addition, we used TCGA clinical data and GEPIA24 and found that high mRNA levels of ZDHHC13 are associated with a survival benefit in melanoma patients." (PMID 30787281, 2019). "However, since the palmitoylation of many targets is likely increased with Palm-B, targeting zDHHC13 is suggested to be a better option in preventing melanoma development; therefore, investigating mechanisms underlying its regulation may offer additional therapeutic strategies." (PMID 40004137, 2025). "Our research identified a dual pathway by which ZDHHC13 stabilizes E-cadherin, thereby inhibiting melanoma metastasis." (PMID 41321310, 2025). "ZDHHC13 expression was significantly reduced in human melanoma samples compared with normal tissues across multiple cohorts, and ZDHHC13 expression levels were even lower in metastatic melanoma samples." (PMID 41321310, 2025). "We crossed our previously generated Tg-Tyr-ZDHHC13 mice with a melanoma mouse model Tyr-Cre-BrafV600E/Pten–/–." (PMID 41321310, 2025). "To explore how SMPD2 is regulated by ZDHHC13, we performed IP followed by mass spectrometry to identify potential substrates of ZDHHC13 in melanoma cells." (PMID 41321310, 2025). "ZDHHC13 suppresses melanoma metastasis by stabilizing E-cadherin and reshaping the immune microenvironment, offering a potential therapeutic target to inhibit tumor progression." (PMID 41321310, 2025). "In contrast, our results showed that ZDHHC13 overexpression significantly inhibited melanoma cell migration and invasion, while ZDHHC13 knockdown markedly enhanced these behaviors." (PMID 41321310, 2025). "It is the most enriched gene in the ARG1+ M2-like TAM cluster and was significantly reduced in TAMs following ZDHHC13 overexpression in melanomas." (PMID 41321310, 2025). "To test this, we overexpressed ZDHHC13 in melanoma cells expressing either WT or C618S CTNND1 and conducted in vitro migration and invasion assays." (PMID 41321310, 2025). "Further validation in melanoma cells confirmed that ZDHHC13 is the primary PAT responsible for CTNND1 palmitoylation." (PMID 41321310, 2025). "By targeting both intrinsic melanoma cell mechanisms and the broader tumor microenvironment, our findings provide a comprehensive framework for understanding ZDHHC13 signaling and its impact on melanoma metastatic progression." (PMID 41321310, 2025). "To investigate the impact of ZDHHC13 on human melanoma, we commenced our study by analyzing data from the TCGA metastatic melanoma cohort." (PMID 41321310, 2025). "Our data also indicated that transgenic ZDHHC13 expression inhibited melanoma metastasis to the lungs." (PMID 41321310, 2025). "To confirm ZDHHC13’s potential tumor-suppressive role in melanoma within an immunocompetent setting, we engineered B16 cells to overexpress ZDHHC13 via lentiviral transduction." (PMID 41321310, 2025). "Our results therefore show that ZDHHC13-activated MC1R palmitoylation plays a critical role in melanoma prevention in vivo." (PMID 30787281, 2019).
melanoma (continued). "The identification here of ZDHHC13 as a critical regulator of MC1R function in vivo offers an alternative and potentially viable approach toward melanoma prevention in highly susceptible individuals." (PMID 30787281, 2019). "Here we report that ZDHHC13 expression correlates with MC1R signaling and survival in human melanoma and that its expression can rescue MC1R RHC variant signaling in vitro and in vivo to suppress UVR-induced melanomagenesis." (PMID 30787281, 2019). "Melanomas were observed in the UVB-exposed Tyr-Cre-BRAFCA/Tg-ZDHHC13/MC1RR151C mice, with the Tyr-Cre-BRAFCA/Tg-ZDHHC13 mice and Tyr-Cre-BRAFCA/Tg-MC1RR151C mice serving as controls." (PMID 30787281, 2019). "Dual functions of ZDHHC13 in melanoma metastasis suppression." (PMID 41321310, 2025). "Next, we aimed to assess whether ZDHHC13 could be a viable target for suppressing melanoma metastasis." (PMID 41321310, 2025). "ZDHHC13 suppresses melanoma growth and metastasis in immunocompetent mice." (PMID 41321310, 2025). "Given that ZDHHC13 increases E-cadherin protein in melanoma cell culture and in vivo, we investigated whether ZDHHC13 could also increase the infiltration of CD103+ immune cells into the melanoma microenvironment." (PMID 41321310, 2025). "We conducted an additional analysis using a human melanoma tissue array (ME551) and observed a strong inverse correlation between ZDHHC13 and SMPD2 protein expression." (PMID 41321310, 2025). "Specifically, ZDHHC13 palmitoylates CTNND1, enhancing E-cadherin stability on the melanoma cell membrane." (PMID 41321310, 2025). "The interaction between ZDHHC13 and CTNND1 was further validated through coimmunoprecipitation experiments in SK-Mel-28 melanoma cells and HEK-293T cells." (PMID 41321310, 2025). "zDHHC13 phosphorylation by AMPK at Ser208 enhanced MC1R S‐acylation, inhibiting UVB‐induced transformation of human melanocytes in vitro and delaying melanoma development in mice." (PMID 39429488, 2024). "Moreover, when the MC1R C315S mouse model was crossed with the melanocyte-specific zDHHC13 transgenic mouse model, UVB-induced melanoma was detected sooner relative to the MC1R R151C mice followed by the wild-type mice." (PMID 40004137, 2025). "Importantly, our data show that concurrent activation of both downstream arms of ZDHHC13 signaling — enhanced CTNND1 palmitoylation and suppression of macrophage-derived MMP12 — produces the most robust inhibition of melanoma metastasis." (PMID 41321310, 2025). "Our research highlights the role of ZDHHC13 in stabilizing E-cadherin to suppress melanoma metastasis through both melanoma-autonomous and nonautonomous mechanisms." (PMID 41321310, 2025). "Given that macrophages comprise over 70% of immune cells in the melanoma TME, the CD103–E-cadherin interactions may play a minor role in ZDHHC13-mediated immune modulation in this context." (PMID 41321310, 2025). "Significantly, ZDHHC13 failed to suppress lung colonization in immunodeficient mice with melanomas expressing C618S CTNND1, but was able to do so in immunocompetent C57BL/6J mice with the same C618S CTNND1–expressing tumors." (PMID 41321310, 2025). "Our results indicated that ZDHHC13 in B16 cells notably increased the proportion of M1-like TAMs, CD8+, CD4+, and NK cells, while diminishing the population of M2-like TAMs in subcutaneously inoculated tumors as well as in tail vain injection–induced melanoma lung metastasis." (PMID 41321310, 2025).
osteoporosis (5 papers, 2010 to 2025). A condition of reduced bone mass, with decreased cortical thickness and a decrease in the number and size of the trabeculae of cancellous bone (but normal chemical composition), resulting in increased fracture incidence. "We previously reported that Zdhhc13 deficient mutant mice had severe osteoporosis at 26 weeks of age." (PMID 24637783, 2014). "While our experiments were carried out in the ENU-generated Zdhhc13 nonsense mutation mouse model which had reduced expression of Zdhhc13, we have also validated the osteoporosis phenotype in our gene-trap mice." (PMID 24637783, 2014). "Our goal in this study was to investigate the pathogenic mechanisms underlying osteoporosis in the Zdhhc13 deficient mice." (PMID 24637783, 2014). "We aimed to understand how a palmitoylation enzyme, Zdhhc13, can affect bone homeostasis with the hope of providing new insights into the biological functions of palmitoylation and the pathogenic mechanisms of human osteoporosis." (PMID 24637783, 2014). "Deficiency of protein palmitoylation in the Zdhhc13 mutant mice could also explain the apparent osteoporosis because palmitoylation regulates osteoblast differentiation through bone morphogenesis protein (BMP)-induced Osterix expression." (PMID 20548961, 2010).
Anxiety (3 papers, 2017 to 2025). Intense feelings of nervousness, tension, or panic often arise in response to interpersonal stresses. "Here, for the first time, we show that Zdhhc13 plays a key role in anxiety-related behaviors and motor function, as well as brain bioenergetics, in a mouse model (luc) carrying a spontaneous Zdhhc13 recessive mutation." (PMID 29038583, 2017).
glioma (2 papers, 2020 to 2025). A benign or malignant brain and spinal cord tumor that arises from glial cells (astrocytes, oligodendrocytes, ependymal cells). "Given the conditions, dysregulated palmitoylation modifications on specific zDHHC enzymes likes zDHHC9, zDHHC13, and zDHHC21 are targeted in AD, HD, schizophrenia, and glioma, suggesting as a therapeutic approach." (PMID 40831763, 2025). "Attesting to its specificity, the expression of ZDHHC13, the homeodomain protein of ZDHHC17, was not related to MAP2K4 expression in glioma tissue." (PMID 31938047, 2020).
pancreatic cancer (2 papers, 2023 to 2024). "For example, ZDHHC13 RNA and protein were highly enriched in esophageal and pancreatic cancer cell lines, and depleted in liver cancer cell lines, while ABHD12 was enriched in kidney and liver cancer cell lines." (PMID 36760531, 2023).
systemic amyloidosis (2 papers, 2010 to 2013). "The lack of Zdhhc13 PAT activity affected palmitoylation of a set of unspecified protein targets and compromised their conformational stability and subcellular localization, eventually causing systemic amyloidosis of both the AA and AL types." (PMID 20548961, 2010).
AA amyloidosis (1 paper, 2023). Secondary amyloidosis is a form of amyloidosis, that complicates chronic inflammatory disorders (mainly rheumatoid arthritis) and is characterized by the aggregation and deposition of amyloid fibrils composed of serum amyloid A protein, an acute phase reactant. "Therefore, a variant in ZDHHC13 might also play a role in systemic AA-amyloidosis in cats." (PMID 38136948, 2023). "ZDHHC13 may be a stronger putative candidate as it plays a role in thyroid gland disease in mice and the thyroid gland is one of the main target organs of AA-amyloidosis in Siamese and Oriental shorthair cats." (PMID 38136948, 2023).
AL amyloidosis (1 paper, 2023). AL Amyloidosis is a plasma cell disorder characterized by the aggregation and deposition of insoluble amyloid fibrils derived from misfolding of monoclonal immunoglobulin light chains usually produced by a plasma cell tumor. "Interestingly, a mutation in ZDHHC13 caused a severe phenotype in mice including systemic AA- and AL-amyloidosis." (PMID 38136948, 2023).
endothelial dysfunction (1 paper, 2025). In vascular diseases, endothelial dysfunction is a systemic pathological state of the endothelium (the inner lining of blood vessels) and can be broadly defined as an imbalance between vasodilating and vasoconstricting substances produced by (or acting on) the endothelium. "Taken together, these data indicate that zDHHC13 palmitoylates PKM2 and accelerates PA‐induced endothelial dysfunction." (PMID 39665133, 2025).
Erythema (1 paper, 2025). Redness of the skin, caused by hyperemia of the capillaries in the lower layers of the skin. "These zDHHC13-deficient mice also displayed abnormalities in their skin including reduced/shortened hairs, skin erythema, and epidermal hyperplasia, in the absence of other characteristics noted with the ENU-induced zDHHC13 mouse model." (PMID 40004137, 2025).
generalized anxiety disorder (1 paper, 2025). An anxiety disorder characterized by excessive and difficult-to-control worry about a number of life situations. "Mendelian randomization identifies palmitoylation genes driving generalized anxiety disorder (GAD) risk, notably ZDHHC5 and ZDHHC13." (PMID 40898659, 2025).
Hyperhidrosis (1 paper, 2017). Abnormal excessive perspiration (sweating) despite the lack of appropriate stimuli like hot and humid weather. "Zdhhc13-deficient mice present with metabolic abnormalities, including non-thyroidal hypermetabolism and hyperhidrosis." (PMID 28526873, 2017).
lactic acidosis (1 paper, 2017). Metabolic acidosis characterized by the accumulation of lactate in the body. "Loss of Zdhhc13 in cortex and cerebellum from 3- and 24 m old hetero- and homozygous male mutant mice resulted in lower levels of Drp1 S-palmitoylation accompanied by altered mitochondrial dynamics, increased glycolysis, glutaminolysis and lactic acidosis, and neurotransmitter imbalances." (PMID 29038583, 2017).
magnesium deficiency (1 paper, 2010). A nutritional condition produced by a deficiency of magnesium in the diet, characterized by anorexia, nausea, vomiting, lethargy, and weakness. "Because our mutant mice had normal serum magnesium and calcium levels and demonstrated no clinical evidence of magnesium deficiency, we propose that the observed phenotypes originated from the loss of the enzymatic function of Zdhhc13 as a PAT." (PMID 20548961, 2010).
metastatic melanoma (1 paper, 2025). A melanoma that has spread from its primary site to another anatomic site. "Clinical data analysis revealed a notable association between increased ZDHHC13 mRNA expression and enhanced survival rates in patients with metastatic melanoma." (PMID 41321310, 2025). "IHC staining revealed that ZDHHC13 protein levels were significantly lower in metastatic melanoma." (PMID 41321310, 2025). "Utilizing the xCell quantification algorithm, we observed a significant relationship between elevated ZDHHC13 mRNA levels, reduced M2 macrophage infiltration, and increased presence of Memory CD4+ T cells in TCGA human metastatic melanoma samples." (PMID 41321310, 2025).